CD44 (CD44 molecule (IN blood group))
Diseases named in the same sentence as CD44 in open-access papers (continued):
Sharing a sentence is not in itself a finding about the gene and the disease.
gastric cancer (continued). "Hence, we performed a meta-analysis to elucidate whether CD44 or CD133 overexpression would correlate with gastric cancer clinicopathology and prognosis and to explain which of these markers would have more clinical value based on the meta-analysis evidence." (PMID 27759647, 2016). "YM155 significantly inhibited sphere formation of gastric cancer cells, suppressed expansion and growth of the formed spheres (cancer stem cell-like cells, CSCs) and downregulated the protein levels of β-catenin, c-Myc, Cyclin D1 and CD44 in gastric cancer cells." (PMID 26771139, 2016). "However, the prognostic roles of CD44 protein in colon and gastric cancer remain controversial." (PMID 27323782, 2016). "In addition, we analyzed the prognostic roles of CD44 mRNA in subtypes of gastric cancer." (PMID 27323782, 2016). "Though FGFR2 and CD44 signals are frequently deregulated and are important in GC growth and maintenance in vitro and in vivo, the cooperative roles of FGFR2 and CD44 in the context of gastric cancer stemness factors have not been studied." (PMID 27107424, 2016). "CD44 has been confirmed as a cancer stem cell marker in a variety of human cancer cell lines and primary tumours, but whether this marker is applicable to gastric cancer (GC) remains unknown." (PMID 23833643, 2013). "Moreover, ablation of CD44 (a gastric cancer stem cell marker) in K19-Wnt1/C2mE mice (i.e., CD44−/−K19-Wnt1/C2mE mice) suppressed gastric tumor growth, suggesting that CD44-targeted therapy may impair tumor growth ability." (PMID 24216700, 2013). "Moreover, CD44 amplification is also found in gastric cancer." (PMID 22606006, 2012). "According to our findings, ASGR2, Bax, CD44, and TIM4 are genes impacted by MPs in gastric cancer cells." (PMID 41378310, 2025). "Research on gastric cancer cells has shown that CD44 increases the production of IL‐8 by CAFs, and in GCTB cancer cells, the SRGN/CD44/FAK system induces osteoclast differentiation from monocytes, supporting tumor progression." (PMID 40542654, 2025). "Downregulation of JMJD3 resulted in a significant decrease in the levels of CD44, SOX2, OCT4, and LIN28 in gastric cancer cells." (PMID 41184226, 2025). "Similarly, serum exosome CD44 concentration was positively correlated with lymph node tumor load and could be used as a potential therapeutic target and non-invasive biomarker for lymph node metastasis in gastric cancer." (PMID 41013561, 2025). "Experimental silencing or knockout of Gal-4 in gastric cancer models has been shown to reduce the levels of activated c-MET and CD44, leading to attenuated cell proliferation and decreased peritoneal dissemination." (PMID 40710343, 2025). "To clarify the function of CD44 in gastric cancer, we analyzed the TCGA-STAD dataset and observed that the expression levels of CD44 in gastric cancer tissues were significantly elevated compared to those in normal tissues (p < 0.001)." (PMID 40069421, 2025). "Previous studies have identified cluster of differentiation 44 (CD44) and aldehyde dehydrogenase (ALDH) activity as key markers of the tumorigenic and drug-resistant CSC subpopulations in gastric cancer." (PMID 39866240, 2025). "Since CD44 and CD133 have also been identified as markers of gastric cancer stem cells, we investigated how the levels of both proteins correlated with NINJ2 expression." (PMID 40518514, 2025). "The overexpression of miR-17-5p markedly elevates the expression of stem cell markers CD44 and EpCAM in MGC-803 gastric cancer cells, augments tumor spheroid forming capacity, and promotes cellular resistance to chemotherapeutic agents." (PMID 40710326, 2025).
gastric cancer (continued). "Previous studies have reported that CD44 directly induces vimentin gene transcription via EMT transcription factors like Slug, thereby facilitating EMT and metastatic progression in gastric cancer." (PMID 40518514, 2025). "CD44v6 was markedly upregulated in gastric cancer tissues, correlating with a worse prognosis and enhancing CSC traits by increasing the expression of key markers such as CD44, CD133, and EpCAM, as well as key transcription factors like Oct-4 and Nanog." (PMID 40069421, 2025). "The expression of CD44 and OCT4 was decreased, while CD24 expression was increased by overexpressing ACAT1 in MKN45 gastric cancer cells." (PMID 39247186, 2024). "IHC assays of stomach cancer tissues also showed that SRGN was mainly expressed in tumour cells, and CD44 tended to be expressed in CAFs and some lymphocytes." (PMID 38862740, 2024). "CD44 and OCT4 have emerged as survival biomarkers in various solid tumors, including gastric cancer." (PMID 39247186, 2024). "SALL4 knockdown downregulates the expression of stemness- and EMT-related genes (OCT4, SOX2, NANOG, C-MYC and CD44) and suppresses the activation of the ERK, STAT3 and NF-κB pathways, thus inhibiting the proliferation and migration of gastric cancer cells." (PMID 38584262, 2024). "We investigated the relationship between ACAT1 and the levels of CD44 and OCT4 in three different gastric cancer cell lines." (PMID 39247186, 2024). "This study expands on BATF2's role in gastric cancer, demonstrating how it interacts with PTEN to suppress the AKT/β-catenin/ABCG2 signaling pathway, impacting stem cell markers like ABCG2, CD44, SOX2, and NANOG, based on in vivo and in vitro analyses." (PMID 39629124, 2024). "Immunofluorescence staining confirmed the presence of CD44 and CD24 proteins on the surface of gastric cancer cells, showing that increased ACAT1 levels suppress CD44 expression and enhance CD24 expression." (PMID 39247186, 2024). "More recent studies on nasopharyngeal cancer, renal cancer, and gastric cancer also found that genistein suppresses Shh and GLI1 signalling, decreasing the expression of CD44 and other stem cell markers." (PMID 38920995, 2024). "Although CD44+CD24+ and CD44+CD54+ cells have clinical relevance in patients with GC, it is still necessary to determine whether these cells with self-renewal capability are true gastric cancer stem cells (GCSCs)." (PMID 36737794, 2023). "Immunohistochemistry was used to detect the expression of FAP, CD10, and GPR77 in CAFs; the EMT markers (N-cadherin, Snail1, and Twist1) and the CSC markers (ALDH1, CD44, and LGR5) in gastric cancer cells." (PMID 37277751, 2023). "The result showed that a significant correlation was found between KMT2A and the stemness-related gene sets, including tumor stemness-related signature (CD44/CD133/Sox2/OCT4) and gastric cancer-specific stemness signature (Sox/FOXM1)." (PMID 38025523, 2023). "Under hypoxic conditions, CD44 expression increased by 3-fold and 2.2-fold, respectively, in SGC7901 and BGC823 gastric cancer cells." (PMID 36846589, 2023). "Contrary to the positive regulatory role of HIF-1α on CD44 and CD24, HIF-1α exhibited a negative regulatory effect on CD133 in a panel of gastric cancer cell lines." (PMID 36846589, 2023). "In gastric cancer, GIAPLINC can modify CD44-dependent cell invasion in cancer cells, which relates to a poor prognosis." (PMID 36741921, 2023). "In cases of G.C., clinical reports frequently highlight upregulation of the cancer stemness markers CD44 and CD133, along with an increase in DCLK-1 expression within gastric carcinomas." (PMID 38136437, 2023). "In three cancer types (i.e., anaplastic thyroid, colorectal, and gastric cancers), mIF consistently illustrated the proximity of some SPP1+ TAMs (SPP1+CD68+) to CAFEndMT (CD44+CD31+)." (PMID 36333338, 2022).
gastric cancer (continued). "The MKN45 cells with GRP78 knockdown exhibited decreased formation of colonies and spheroids and decreased expression of gastric cancer stem cell–like markers (LGR5, CD24, CD44, and ALDH1) and stemness-related transcriptional factors (SOX2 and Nanog)." (PMID 35740372, 2022). "Ectopic AKAP8L in gastric cancer cells and spheroids elevated the expression of stem cell markers, including Lgr5, CD133, CD44, Oct4, Sox2, as determined by qPCR, Western blot analysis." (PMID 36522343, 2022). "Knockdown of GRP78 expression or inhibition of GRP78 by ISL downregulated CD24, CD44, LGR5, SOX2, and Nanog in gastric cancer in our study." (PMID 35740372, 2022). "Gastric cancer stemness can be determined by investigating the expression of cell surface markers, namely CD24, CD44, and LGR5, and stemness-related transcriptional factors, namely Nanog and SOX2." (PMID 35740372, 2022). "A total of 3806 disease targets of “malignant neoplasm of stomach” were obtained from the DisGeNET database and used for GSEA of CD44 differential cancer." (PMID 36316684, 2022). "At the cellular level, patients with gastric cancer have decreased numbers of CD3+ and CD8+ cells and an increase in CD4+, CD19+, CD44+, CD25+, and NK compared to a disease-free control." (PMID 34862564, 2022). "By using the TIMER database, we analysed the correlation between the expression of CD44 and 6 kinds of infiltrating immune cells, namely, B cells, CD8+ T cells, CD4+ T cells, macrophages, neutrophils and dendritic cells, in gastric cancer." (PMID 36316684, 2022). "A positive correlation was observed between E2F1 and BMI1 (r = 0.422, p < 0.05), CD44 (r = 0.634, p < 0.05), OCT4 (r = 0.456, p < 0.05), and Nanog (r = 0.337, p < 0.05) in gastric cancer tissues." (PMID 33986804, 2021). "Similar to the high expression of CD44, the increased expression of CD90 has been observed in spheroid populations of gastric cancer cells along with a tumorigenic capacity in vivo." (PMID 33562727, 2021). "The direct link between circRNAs and CD44 was initially reported in gastric cancer (GC) cells." (PMID 32943996, 2020). "Expression of both CD44 and OPN has been reported to correlate with the worse prognosis for human gastric cancer patients." (PMID 31901081, 2020). "In respect to CTCs, CD44 has been identified as CSC marker of gastric cancer and most of the CTC-positive patients showed CD44-positive CTCs." (PMID 31446534, 2020). "CD44 was the first marker used to identify Gastric Cancer (GC) Stem Cells (GCSCs)." (PMID 32296643, 2020). "CD44 with overexpression of HH/SMO pathway genes and some self-renewal marker proteins (SOX2, OCT4 and NANOG) in several gastric cancer cell lines were found." (PMID 32962123, 2020). "To better illustrate the effect of MgCl2 on the cancer stemness, we performed flow cytometry to analyze the expression of cancer stem cells markers CD44 and CD133 in immortalized normal gastric cells Ges1 and gastric cancer cells MKN1." (PMID 33363019, 2020). "In the present work and a previous study, we successfully isolated GCSC spheres from gastric cancer cell lines, MKN28 and SGC-7901, and found that GCSCs express high levels of stem cell surface markers, including CD24, CD44, and OCT4." (PMID 29422082, 2018). "CD44 overexpression antagonized SALL4 knock-down-mediated inhibition of gastric cancer cell proliferation, migration, and invasion in vitro and gastric cancer growth in vivo." (PMID 29747682, 2018). "The sphere-forming ability and in vivo tumorigenicity of patient-derived gastric cancer stem-like cells, expressing HER2 and the CD44 protein, were also inhibited." (PMID 28284008, 2018). "In gastric cancer, GAPLINC promotes the invasion of gastric cancer cells by binding to miR-211–3p, which upregulates the expression of CD44." (PMID 29970131, 2018).
gastric cancer (continued). "Since there are no consensus cell surface markers for putative cancer stem cells in gastric cancer, we examined changes in the following markers: CD24, CD33, CD44, CD90 and CD133 that are reported in the literature." (PMID 28404967, 2017). "The second isoform of CD44, CD44V8-10, is an important marker for human gastric cancer and increases tumor initiation in gastric cancer cells." (PMID 29220461, 2017). "Based on the expression of cell surface markers, such as CD44 and CD133, CSCs have been isolated from gastric cancer cell lines, lung tumor tissues, and other cancers." (PMID 28430578, 2017). "Our results suggested that CD44 expression could be used as a marker for the prediction of gastric cancer development, particularly in patients with precancerous gastric lesions carrying AG or GG, who were selected to surveillance follow-up for gastric cancer prevention." (PMID 29445738, 2017). "Another explanation for this observation is that the CD44 protein expression may not result from CD44 mutation of rs187116 but mutations in genes that regulate carcinogenesis could result in uncontrolled CD44 expression and gastric cancer." (PMID 29445738, 2017). "Although the G allele appeared to be associated with the risk of CD44 expression in gastric cancer, however no statistically significant was observed in precancerous gastric lesions; the results might reflect statistical fluctuation due to the small number of patients in each group." (PMID 29445738, 2017). "In conclusion, our findings suggest that CD44 is a downstream target gene of SALL4 and is partially responsible for the oncogenic roles of SALL4 in gastric cancer." (PMID 27819668, 2016). "Since CD44 showed a decreased expression in SALL4 knockdown gastric cancer cells, we then focused on the regulatory role of SALL4 in CD44 expression." (PMID 27819668, 2016). "The results of western blot showed that the expression of CD44, SALL4, c-MYC, Oct4, Nanog, and Sox2 proteins also increased in 1 μM and 10 μM DIM-treated gastric cancer cells." (PMID 26918831, 2016). "Since the qPCR analysis of gastric cancer tissues only detected up-regulated expression of LGR5, CD44 and PRRX1 among the putative CSC markers, stemness regulators and EMT inducers, we next tried to use GC cell lines in vitro to confirm this result." (PMID 28033430, 2016). "Combined detection of CD44 and CD133 expression can be an even more effective tool for pathological diagnosis and prognostic prediction of patients with gastric cancer in clinical applications." (PMID 27759647, 2016). "In summary, this study demonstrates the value of CD44 and CD133 as 2 significant clinical indicators for patients with gastric cancer." (PMID 27759647, 2016). "CD44 has been demonstrated to be a marker of human gastric cancer CSC and CD44+ gastric cancer cells have stronger tumorigenic than CD44− gastric cancer cells." (PMID 26771139, 2016). "Patients with positive CD44/CD133 expressions were evaluated by IHC, and the specimens were derived from gastric cancer tissues by either biopsy or surgical resection." (PMID 27759647, 2016). "In this study, we observed the downregulation of CD44 in stable and inducible SALL4 knockdown gastric cancer cells." (PMID 27819668, 2016). "To further investigate the effect of CD44, Shh, and Gli1 in gastric cancer progression, we analysed the correlations between the level of CD44, Shh, and Gli1 protein and clinicopathological characteristics of GC." (PMID 26839535, 2016). "Taken together, these results indicate that CD44 overexpression antagonizes SALL4 knockdown-mediated inhibition of the proliferation, migration and invasion of gastric cancer cells in vitro." (PMID 27819668, 2016). "We also detected the expression of Mel-18, CD44, CD133, Oct4, Sox2, and Gli1 expressions in gastric cancer cells using Western blot assay or QRT-PCR." (PMID 27542229, 2016).
gastric cancer (continued). "In recent years, CD44 and CD133 have been identified as 2 common used cancer stem cell (CSC) markers in gastric cancer." (PMID 27759647, 2016). "We found that YM155 induced apoptosis of gastric cancer cells, inhibited expansion of gastric CSCs and expression of CSC molecules CD44 and β-catanin and suppressed gastric cancer xenograft growth." (PMID 26771139, 2016). "Despite some controversies, CD44, CD90 (Thy1), and EpCAM (CD326) are thought to enrich gastric cancer stem cells (GCSCs)." (PMID 27107424, 2016). "We also detected the expression of stem cell markers including Oct-4, Sox-2, Glil, CD44, and CD133 in the primary sites of gastric cancer and analyzed the correlation between these stem cell markers and Bmi-1 by spearman rank correlation test." (PMID 27644439, 2016). "In conclusion, CD44 and FGFR2 maintain stemness in gastric cancer by differentially regulating c-Myc transcription." (PMID 27107424, 2016). "We found that the expression of β-catenin and its downstream targets CD44, c-MYC, and Cyclin-D3 were significantly up-regulated in gastric cancer cells after treatment with low level of DIM." (PMID 26918831, 2016). "However, the expression of CD44, a gastric cancer stem cell marker, was associated with improved survival in the group who received the SHH inhibitor suggesting that SHH inhibition may only be effective in those with high CD44 expression." (PMID 25784931, 2015). "In conclusion, both CD44 and CD47 were highly expressed in gastric cancer cells, and their higher expressions correlated with higher proliferation and tumorigenicity in vitro and in vivo." (PMID 26077800, 2015). "Coexpression of CD44 and CD133 in gastric cancer samples displayed a positive correlation using t-test and Fisher's exact test." (PMID 25635255, 2014). "This study aimed to explore changes in CD44 and CD24 expression levels in patients with gastric cancer and to assess their prognostic values." (PMID 25212506, 2014). "More recently, CD45-/ CD90+, CD133+ and CD44 + have been identified as CSC markers for hepatoma osteosarcoma and stomach cancer, respectively." (PMID 24670249, 2014). "Multivariate analyses identified CD44 expression, TNM stage, and lymphovascular invasion as independent prognostic factors of poor patient survival in gastric cancer." (PMID 25212506, 2014). "In gastric cancer, HER2 cooperates with CD44 and down-regulates miR-139 via histone H3K9 deacetylation in the miR-139 promoter region." (PMID 24885920, 2014). "Previous investigation of the correlation between CD24/CD44 expression and gastric cancer revealed that CD24(+) patients had a higher likelihood of gastric cancer recurrence than CD24(−) patients." (PMID 25212506, 2014). "CD44 has been identified as gastric cancer (GC) stem cell (CSC) marker." (PMID 24963492, 2014). "CD44 expression was correlated with ZEB1 expression and was inversely correlated with the E-cadherin levels in the gastric cancer." (PMID 25197668, 2014). "Gastric cancer stem-like cells (GCSCs) have recently been reported in GC cell lines and primary tumors with the markers CD71–, EpCAM+/ CD44+ and CD90+ identifying them." (PMID 23554769, 2012). "The role of CD44 and CD24 expression in gastric carcinoma has been explored for nearly thirty years." (PMID 22839505, 2012). "Similarly, we observed a significant increase in CIC markers, such as CD44, CD44v9, and CD24, in ECF-R gastric cancer cells compared with those in the parental cells." (PMID 40518514, 2025). "SNORA37 directly binds to cap methyltransferase 1 (CMTR1) to facilitate its interaction with ELAVL1, resulting in nuclear retention and activity of ELAVL1 in regulating alternative splicing of CD44, which indicates the roles of SNORA37/CMTR1/ELAVL1 feedback loop in gastric cancer progression." (PMID 39815331, 2025). "In gastric cancer, AQP3 is overexpressed and correlates with the CSC marker CD44." (PMID 40806720, 2025).